CFTR (CF transmembrane conductance regulator)
Diseases named in the same sentence as CFTR in open-access papers (continued):
Sharing a sentence is not in itself a finding about the gene and the disease.
cystic fibrosis (continued). "Mutations in the CFTR gene cause cystic fibrosis, the most common autosomic recessive disorder among Caucasians." (PMID 31231217, 2019). "The common mutations should be identified by sequencing the entire CFTR gene in adequate number of cystic fibrosis patients in order to design a mutation panel for common regional mutations." (PMID 31126253, 2019). "Cystic fibrosis is an autosomal recessive disease with mutations in the CF transmembrane conductance regulator (CFTR) gene causing a life-limiting multisystemic disease." (PMID 31772562, 2019). "Cystic fibrosis is an inherited disease caused by a mutation that affects the cystic fibrosis transmembrane regulator (CFTR), leading to the generation of a dysfunctional protein impeding chloride from reaching the cell surface." (PMID 31817881, 2019). "Cystic fibrosis is caused by defective Cystic Fibrosis Transmembrane Conductance Regulator (CFTR) protein." (PMID 31019198, 2019). "Mutations in the cystic fibrosis transmembrane conductance regulator (CFTR) gene cause the life-limiting hereditary disease, cystic fibrosis." (PMID 30800069, 2019). "Cystic fibrosis is a genetic disease associated with the defective function of the cystic fibrosis transmembrane conductance regulator (CFTR) protein that causes obstructive disease and chronic bacterial infections in airway epithelia." (PMID 31683989, 2019). "Cystic fibrosis is an autosomal recessive disease of inflammation, obstruction and infection caused by mutations in the CF transmembrane conductance regulator gene." (PMID 30857526, 2019). "Cystic fibrosis is caused by genetic mutations that lead to the reduced activity or expression of the CFTR at the cell surface of epithelial cells." (PMID 31683989, 2019). "Cystic fibrosis is a lethal inherited disease caused by mutations in the CF transmembrane conductance regulator (CFTR) gene, which result in impairment of CFTR mRNA and protein expression, function, stability or a combination of these." (PMID 32153386, 2019). "Cystic fibrosis is caused by the presence of severe mutations (such as ∆F508, the most frequent CFTR mutation in Caucasian population) in both copies of the CFTR gene." (PMID 31024732, 2019). "Cystic fibrosis genetic therapies rely on delivering DNA or RNA, which encodes the CFTR protein or on the restoration of the CFTR gene (genome editing) or the CFTR mRNA (mRNA editing)." (PMID 30873022, 2019). "For example, mutations in the CFTR chloride channel, which is encoded by ABCC7 gene, result in abnormal solute transportation in lungs and cause cystic fibrosis in humans." (PMID 31105571, 2019). "One triallelic site harbors the ΔF508 mutation in CFTR (rs113993960), causal for cystic fibrosis in the homozygous state, an allele that is present in approximately 1% of Europeans and Americans34,35." (PMID 31695094, 2019). "Cystic fibrosis is caused by mutations in the CFTR (cystic fibrosis transmembrane conductance regulator) gene." (PMID 31477148, 2019). "The importance of the channel is underscored by the hereditary disease cystic fibrosis, where loss of anion permeability through CFTR has major detrimental effects in the lungs, gastrointestinal and reproductive tracts." (PMID 30547226, 2019). "CFTR modulator therapy with ivacaftor is a treatment option for Cystic Fibrosis patients with at least one copy of a R117H-7T mutation in the CFTR gene." (PMID 30975115, 2019). "Cystic fibrosis is a hereditary disease due to mutations in the CFTR gene and causes mortality in humans mainly due to respiratory infections caused by Pseudomonas aeruginosa." (PMID 30728389, 2019). "Cystic fibrosis results from deficient CF transmembrane conductance regulator (CFTR) protein activity leading to defective epithelial ion transport." (PMID 31803183, 2019).
cystic fibrosis (continued). "Among the requests for PD of inherited genetic diseases, one of the most frequent is cystic fibrosis, an autosomal recessive disease due to about 2000 different mutations in the gene encoding the CF transmembrane regulator (CFTR) protein." (PMID 31877800, 2019). "For example, individuals with the 3849+10 kb C-T mutation exhibit a mild cystic fibrosis phenotype due to the production of mutant and wild-type CFTR mRNA and there is a case report of a homozygous affected man being fertile." (PMID 31665287, 2019). "Both A subunits reduce degradation of F508del CFTR, the major mutant protein responsible for cystic fibrosis and N370S glucocerebrosidase (GCC) causing the Gaucher glucosylceramide lysosomal storage disease." (PMID 30875878, 2019). "Strikingly, CBAVD is also associated with mild cystic fibrosis, a progressive lung disease due to mutations in cystic fibrosis transmembrane conductance regulator (CFTR), and is the most common autosomal recessive disorder in Caucasians." (PMID 30956978, 2019). "For example, an enhanced understanding of the genetic mutations within CFTR which cause Cystic Fibrosis has improved treatment for many sufferers." (PMID 33467340, 2019). "Cystic fibrosis is caused by mutations in the gene encoding the epithelial chloride channel CF transmembrane conductance regulator (CFTR) protein." (PMID 31251792, 2019). "When specifically considering cystic fibrosis in humans, and assuming equilibrium, we estimate that being a heterozygous CFTR variant carrier confers a selective advantage of at least 3% (depending on our assumption regarding Nn)." (PMID 31316137, 2019). "Cystic fibrosis is caused by mutations of the cystic fibrosis transmembrane conductance regulator (CFTR) gene that codes for the ATP-binding cassette (ABC) anion channel, CFTR." (PMID 31370288, 2019). "In one example, a silent mutation in CFTR, the gene encoding the chloride ion channel that is linked to cystic fibrosis, results in decreased protein levels specifically in bronchial epithelial cells." (PMID 31407949, 2019). "Further, a different variant at the same position, CFTR c.473G > C has been previously reported in a case of Cystic fibrosis." (PMID 30760291, 2019). "Cystic fibrosis is an autosomal recessive disorder characterized by a mutation in the CF transmembrane conductance regulator (CFTR) gene." (PMID 31824646, 2019). "Cystic fibrosis DNA testing was performed by Abbot CFv3 commercial laboratory test for 32 of the most common CFTR mutations, and concluded the patient was heterozygous for del." (PMID 31187952, 2019). "This question is particularly important in light of a potential role of human SLC26A9 to compensate for the loss of CFTR mediated Cl– transport in patients suffering from cystic fibrosis (Balázs and Mall, 2018; Mall and Galietta, 2015)." (PMID 31339488, 2019). "Mutations in the cystic fibrosis transmembrane conductance regulator (CFTR) gene cause cystic fibrosis —the most common life-threatening autosomal recessive disease in Caucasian populations." (PMID 32153386, 2019). "ToF-SIMS has also been employed in lipidomics profiling of lung tissue from Pseudomonas aeruginosa infected Cystic Fibrosis Transmembrane Conductance Regulator deficient (CFTR−/−) mice." (PMID 31296897, 2019). "Cystic fibrosis is a multisystem autosomal recessive disease caused by a mutation in the CF transmembrane conductance regulator (CFTR) gene." (PMID 31583102, 2019). "Cystic fibrosis is the most common genetic disease in the Caucasian population, caused by mutations in the cystic fibrosis transmembrane conductance regulator (CFTR) gene." (PMID 31780953, 2019). "Cystic fibrosis is a multisystem disease caused by mutations in the cystic fibrosis transmembrane regulator (CFTR) gene, and represents the most common life-shortening autosomal recessive disease in Caucasians." (PMID 31007939, 2019).
cystic fibrosis (continued). "Cystic fibrosis results from mutations in the cystic fibrosis transmembrane conductance regulator (CFTR) gene that functions in modulating chloride ion transport across epithelial cells." (PMID 31447806, 2019). "Cystic Fibrosis, an autosomal recessive disease that affects approximately 1 in 2,500 Caucasian newborns, is caused by mutations in the cystic fibrosis transmembrane conductance regulator (CFTR) gene." (PMID 31065288, 2019). "The most frequent cause of the life-limiting genetic disease cystic fibrosis is the F508del mutation in the cystic fibrosis transmembrane conductance regulator (CFTR)." (PMID 30969810, 2019). "In one of the first clinical studies, DOTAP was utilized to deliver the CFTR gene, which is abnormal/deficient in patients with cystic fibrosis, to the lung parenchyma of CF patients." (PMID 30249040, 2018). "Enteroids have also contributed to the understanding of cystic fibrosis caused by mutations in the cystic fibrosis transmembrane conductance regulator (CFTR) using a swelling assay." (PMID 29670862, 2018). "Cystic fibrosis is a genetic disease caused by mutations in the CFTR gene, whereas chronic obstructive pulmonary disease (COPD) is mainly caused by environmental factors (mostly cigarette smoking) on a genetically susceptible background." (PMID 29849481, 2018). "Cystic fibrosis is an autosomal recessive disease caused by the presence of mutations in both alleles at the cystic fibrosis transmembrane conductance regulator (CFTR) gene, and is the most common genetic disease in Caucasian populations." (PMID 30050169, 2018). "Cystic fibrosis is mainly caused by the deletion of Phe 508 (ΔF508) in the cystic fibrosis transmembrane conductance regulator (CFTR) protein that is thus withheld in the endoplasmic reticulum and rapidly degraded by the ubiquitin/proteasome system." (PMID 29316712, 2018). "Cystic fibrosis is caused by a mutation in the gene that regulates the production of the cystic fibrosis transmembrane regulator (CFTR)." (PMID 29970830, 2018). "Cystic fibrosis (MIM: 219700) is caused by dysfunction of the CF transmembrane conductance regulator (CFTR [MIM: 602421])." (PMID 29581887, 2018). "The mutation F508del, responsible for a majority of cystic fibrosis cases, provokes the instability and misfolding of the CFTR chloride channel." (PMID 30618756, 2018). "Cystic fibrosis is a recessive autosomal disease caused by mutations in the CFTR (cystic fibrosis transmembrane conductance regulator) gene located on the long arm of chromosome 7." (PMID 30581723, 2018). "Cystic fibrosis is a genetic disease caused by a mutation of the gene coding for the protein CFTR (cystic fibrosis transmembrane conductance regulator)." (PMID 29422673, 2018). "Mutations of CFTR cause cystic fibrosis, the most common lethal congenital disease in Caucasians (Quinton 1999, Riordan 2008)." (PMID 29930176, 2018). "The cell line CFBE41o– expresses a proteoform of the Cystic Fibrosis Transmembrane Conductance Regulator (CFTR) with a deletion of phenylalanine 508 (∆F508 CFTR) which is the underlying cause of the genetic disease Cystic Fibrosis in over 70% of patients." (PMID 29899466, 2018). "Cystic fibrosis is a disease resulting from defective ion transport caused by mutations in the cystic fibrosis transmembrane conductance regulator (CFTR) gene." (PMID 30540818, 2018). "Cystic fibrosis is caused by mutations in the gene encoding the cystic fibrosis transmembrane conductance regulator (CFTR) protein." (PMID 30283433, 2018). "Cystic fibrosis is a chronic disease caused by mutations in the CF transmembrane conductance regulator (CFTR) gene, which encodes for a channel expressed at the apical surface of epithelial tissues." (PMID 30416443, 2018). "Cystic fibrosis is caused by mutations in the cystic fibrosis transmembrane conductance regulator (CFTR) gene and remains the most common life-shortening diseases affecting the exocrine organs." (PMID 30349480, 2018).
cystic fibrosis (continued). "Mutations of cystic fibrosis transmembrane conductance regulator (CFTR) cause cystic fibrosis with a multitude of clinical manifestations." (PMID 29449653, 2018). "Cystic fibrosis is the most common life-shortening genetic disease and is caused by mutations in the cystic fibrosis transmembrane conductance regulator (CFTR) gene." (PMID 30540818, 2018). "Similar personalized medicine approaches have been successful for cystic fibrosis, in which different drug treatments have been developed for patients with different classes of CFTR mutations." (PMID 29794150, 2018). "In humans, mutations in the CFTR gene that impair CFTR activity cause a severe disease called cystic fibrosis." (PMID 30105226, 2018). "We tested the effect of spautin-1 on F508del-CFTR since it is an inhibitor of USP10 deubiquitinase and of autophagy, a target and a biological process that have been associated with cystic fibrosis and mutant CFTR." (PMID 30618756, 2018). "Genotype imputation using the 1000 Genomes Project (1KG; 2504 individuals) displayed poor coverage at the causal cystic fibrosis transmembrane conductance regulator (CFTR) locus for the International CF Gene Modifier Consortium." (PMID 29581887, 2018). "Cystic fibrosis phenotype heterogeneity cannot be directly attributed to the type of mutation affecting the gene encoding the CFTR protein." (PMID 29915289, 2018). "Cystic fibrosis results from a defective transmembrane conductance regulator (CFTR) gene, which encodes a protein that facilitates the transport of salt and water in and out of cells." (PMID 29888417, 2018). "For example, it has been seen that downregulating the ATPase activity of Hsp90, by displacing Aha1 from Hsp90 complex, can rescue misfolding of the delta F508 mutant CFTR that causes cystic fibrosis." (PMID 29930942, 2018). "Cystic fibrosis is the most common inherited life-shortening condition, characterized by mutations in the CF transmembrane conductance regulator (CFTR) gene." (PMID 29922270, 2018). "The cystic-fibrosis-phenotypic mutation V232D, which affects the center of CFTR’s fourth transmembrane helix (TM4), belongs to a large group of disease-linked nonpolar-to-polar mutations within transmembrane domains that severely inhibit maturation of CFTR8." (PMID 30302398, 2018). "Coding regions and exon-intron boundaries in the CFTR gene from 6 cystic fibrosis patients with a known mutation status were sequenced." (PMID 29466940, 2018). "For example, CFTR ∆F508, the most common cystic fibrosis-causing mutation, is associated with enhanced lysosomal degradation." (PMID 30487393, 2018). "Cystic fibrosis is a genetic disease caused by mutations in the cystic fibrosis transmembrane conductance regulator (CFTR) gene." (PMID 30966479, 2018). "Cystic fibrosis is a recessive genetic disorder caused by an abnormality of the CFTR gene, resulting in production of thick mucus particularly in the lungs and pancreas and leading to recurrent infections, breathing difficulties and digestive problems." (PMID 30524155, 2018). "Cystic fibrosis is one of the most common lethal genetic diseases caused by mutations in the CF transmembrane conductance regulator (CFTR) gene." (PMID 29731717, 2018). "Cystic fibrosis is an autosomal recessive disorder that is caused by a mutation in the CF transmembrane conductance regulator (CFTR) protein." (PMID 30397565, 2018). "Cystic fibrosis is a progressive, chronic and debilitating genetic disease caused by mutations in the CF Transmembrane-Conductance Regulator (CFTR) gene." (PMID 30538635, 2018). "Cystic fibrosis is an autosomal recessive disease caused by mutations in the cystic fibrosis transmembrane conductance regulator (CFTR) gene that encodes a cAMP-regulated anion channel." (PMID 30405068, 2018). "Cystic fibrosis is an autosomal recessive condition caused by mutations in the cystic fibrosis transmembrane conductance regulator (CFTR; MIM 602421) gene." (PMID 30231496, 2018).
cystic fibrosis (continued). "After upstream filtering, only one disorder, cystic fibrosis, was found to show a high risk, as both members of the couple exhibited a mutation in CFTR." (PMID 29368589, 2018). "Mutations in the CFTR channel are known to cause cystic fibrosis, which is characterized by the accumulation of viscous mucus, because of impaired fluid transport." (PMID 30463370, 2018). "Defective versions of this protein, caused by CFTR gene mutations, can lead to the development of cystic fibrosis and congenital bilateral aplasia of the vas deferens (CBAVD)." (PMID 29766145, 2018). "Cystic Fibrosis is an autosomal recessive genetic disorder caused by mutations in the cystic fibrosis transmembrane conductance regulator (CFTR) gene." (PMID 29924856, 2018). "Cystic fibrosis is a genetic disease that is the result of a mutation in the gene that encodes the cystic fibrosis transmembrane conductance regulator (CFTR)." (PMID 29324908, 2018). "Homozygous mutations in the CFTR gene cause cystic fibrosis but heterozygotes seem to be somewhat protected from certain other diseases, such as cholera and typhoid fever." (PMID 28405812, 2017). "Cystic fibrosis, caused by mutations in the cystic fibrosis transmembrane conductance regulator (CFTR), is characterized by defective Cl- and HCO3- epithelial ion transport." (PMID 29281691, 2017). "Mutations in the CFTR gene cause cystic fibrosis, a disease that leads to progressive respiratory illness and other complications of phenotypic variance resulting from perturbations of this protein interaction network." (PMID 29403380, 2017). "Cystic fibrosis is an autosomal recessive disorder caused by mutations in the cystic fibrosis transmembrane conductance regulator (CFTR)." (PMID 28623308, 2017). "Here, we describe a high efficiency strategy for editing of three different rare CFTR mutations which together account for about 3% of individuals with Cystic Fibrosis." (PMID 28863137, 2017). "Cystic fibrosis is hereditary as a result of a loss of function gene mutation in the cystic fibrosis transmembrane conductance regulator (CFTR) protein." (PMID 28993732, 2017). "Cystic fibrosis is caused by mutations in the CFTR chloride channel, leading to reduced airway surface liquid secretion." (PMID 28983075, 2017). "Mutations in the CFTR gene [MIM: 602421] cause the autosomal‐recessive genetic disease cystic fibrosis." (PMID 28667089, 2017). "Other studies have shown that miRNAs play a role in the posttranscriptional regulation of CFTR expression for both the wild-type protein and the most common mutation in cystic fibrosis, ΔF508 CFTR." (PMID 29167681, 2017). "Lung disease progression is variable among cystic fibrosis patients and depends on DNA mutations in the CFTR gene, polymorphic variations in disease modifier genes, and environmental exposure." (PMID 28289476, 2017). "CFTR, which has been identified as the mutated gene in cystic fibrosis patients, is considered an atypical ATP-binding cassette (ABC) transporter which is activated by phosphorylation and ATP hydrolysis." (PMID 28439270, 2017). "For example, cystic fibrosis, a disease defined by mutations in the cystic fibrosis transmembrane conductance regulator (CFTR) gene, is characterized by chronic airway infection and inflammation." (PMID 28811631, 2017). "Cystic fibrosis is caused by mutations in the gene encoding the cystic fibrosis transmembrane conductance regulator (CFTR) channel, which can result in chronic lung disease." (PMID 28983075, 2017). "Cystic Fibrosis is the most common monogenic disease among people of Western European descent and caused by mutations in the CFTR gene." (PMID 28846703, 2017). "For instance, CFTR, the gene in which some mutations lead to cystic fibrosis, is the farthest above expectation (p-value < 0.004)." (PMID 28957316, 2017). "Cystic fibrosis is a lethal monogenic disease caused by mutations in the cystic fibrosis transmembrane conductance regulator (CFTR)." (PMID 29167681, 2017).